ZNF609 (zinc finger protein 609)
Diseases named in the same sentence as ZNF609 in open-access papers (continued):
Sharing a sentence is not in itself a finding about the gene and the disease.
tumor (continued). "In vivo, animal experiments displayed that depletion of circ-ZNF609 restrained the tumor volume and weight from mice, and reduced proliferation-related protein levels in tumor tissues, suggesting that circ-ZNF609 functioned as an oncogenic role in TP progression." (PMID 35135416, 2022). "When circ-ZNF609 is overexpressed in tumor tissues, it could result in poor overall survival, and it positively correlated with lymph node metastasis and advanced TNM or clinical stage." (PMID 35938040, 2022). "Overexpression of circ-ZNF609 contributed to increases in tumor volume and weight in vivo." (PMID 33976745, 2021). "Furthermore, the results of qRT-PCR revealed that circ-ZNF609 and PLK1 expression were increased in the tumor tissues of the LV‐circ-ZNF609 group, while miR‐1224-3p expression was significantly decreased." (PMID 33976745, 2021). "Moreover, circ‐ZNF609 exerts an essential role in various non‐tumour diseases under different molecular mechanisms." (PMID 34697887, 2021). "We show that circRNA zinc finger protein 609 (circZNF609) interacts with several mRNAs increasing the final protein levels, which in the case of the cytoskeleton-associated protein 5 (CKAP5) leads to a stabilized microtubule cytoskeleton and an enhanced tumor cell proliferation." (PMID 35434270, 2022). "In this study, we aimed to identify the role and mechanism of circ-ZNF609 in TC, and we hypothesized that circ-ZNF609 may bind to miR-514a-5p to inhibit cell proliferation, metastasis, and tumor growth, which may pose a new prospective target for the therapy of TP." (PMID 35135416, 2022). "The circ-ZNF609/miR-501-3p axis was targeted to upregulate the expression of hexokinase 2 (HK2), a key enzyme of glycolysis, and then improved the radioresistance of tumor cells both in vitro and in vivo." (PMID 35938040, 2022). "Additionally, mouse experiments with circ-ZNF609 knockdown with or without miR-514a-5p depletion showed that tumor growth was promoted after miR-514a-5p was knocked down." (PMID 35135416, 2022). "ARMS is the most aggressive RMS subtype and many pathways involved in cell proliferation are altered in this tumor, meaning that the effects of circ-ZNF609 alone may not be sufficient for a significant reduction in the rate of cell growth." (PMID 30670781, 2019).
cardiovascular diseases (1 paper, 2022). "In this study, we reported that circ-ZNF609 modulated the activity of Hippo-YAP signaling in response to cardiomyocyte injury, indicating that circ-ZNF609 might be a potential therapeutic target for cardiovascular diseases." (PMID 35474903, 2022).
ZNF609 also shares sentences with these, for which no sentence is quoted: esophageal squamous cell carcinoma (2 papers); acute myocardial infarction (1); bladder cancer (1); diabetes (1); Ewing sarcoma (1); Hypertension (1); laryngeal squamous cell carcinoma (1); muscle atrophy (1); myotonic dystrophy type 1 (1); neuropathic pain (1); non-small cell lung carcinoma (1); oesophagal cancer (1); papillary thyroid cancer (1); renal cell carcinoma (1); retinal (1).